MYC (MYC proto-oncogene, bHLH transcription factor)
Diseases named in the same sentence as MYC in open-access papers (continued):
Sharing a sentence is not in itself a finding about the gene and the disease.
diffuse large B-cell lymphoma (267 papers, 2011 to 2026). "Correlation with known diffuse large B-cell lymphoma markers showed that high expression of MYC, BCL2, and ENO3 was associated with worse outcome." (PMID 36358737, 2022). "Fusions involving the immunoglobulin (IG) loci and one of BCL2, BCL6, or MYC are hallmark aberrations of diffuse large B-cell lymphoma and are hard to detect owing to the poor mappability of the IG loci." (PMID 33441414, 2021). "Furthermore approximately 15–30% of diffuse large B-cell lymphomas (DLBCL) has a MYC translocation, often in combination with partner mutations, which is a negative predictor of disease outcome." (PMID 36792656, 2023). "A more clinically relevant diagnostic category within the WHO might be “MYC-driven diffuse large B-cell lymphoma”." (PMID 22511926, 2012). "MYC/BCL2 double expression (DE) is associated with poor prognosis in patients with diffuse large B-cell lymphoma (DLBCL) receiving rituximab, cyclophosphamide, doxorubicin, vincristine, and prednisolone (R-CHOP)." (PMID 38485822, 2024). "Various types of MYC gene mutations are present in diffuse large B-cell lymphoma (DLBCL) and show different impacts on MYC function and clinical outcomes." (PMID 38239638, 2023). "MYC gene rearrangements in diffuse large B-cell lymphoma (DLBCL) patients are associated with poor prognosis." (PMID 34476551, 2022). "Double-expressor diffuse large B cell lymphoma (DE-DLBCL) co-expresses MYC and BCL-2 as determined by immunohistochemistry (IHC)." (PMID 40145086, 2025). "The pathogenic mechanisms underlying double-expressor diffuse large B-cell lymphoma (DE-DLBCL), specifically related to the myelocytomatosis oncogene (MYC) and B-cell lymphoma 2 (BCL2), are not yet fully understood." (PMID 40426926, 2025). "A study previously demonstrated that mepacrine induced G0/G1 cell cycle arrest and apoptosis in diffuse large B‐cell lymphoma cell lines in a dose‐dependent manner and downregulate MYC cyclin‐dependent kinase 4/6 expression." (PMID 41025936, 2025). "NEAT-1 promotes lymphomagenesis and B-cell proliferation through a MYC-regulated mechanism in diffused large B-cell lymphoma, and it has been reported to be overexpressed in patients with diffused large B-cell lymphoma." (PMID 39184920, 2024). "The proto-oncogene MYC is frequently dysregulated in patients with diffuse large B-cell lymphoma (DLBCL) and plays a critical role in disease progression." (PMID 38785546, 2024). "MYC gene rearrangement rate in diffuse large B-cell lymphoma is about 10%, and R-CHOP treatment has poor efficacy for DLBCL patients with MYC gene rearrangement." (PMID 36352191, 2023). "A study using high-resolution array comparative genomic hybridization to identify chromosomal copy number aberrations in 12 dogs with Diffuse Large B-cell Lymphoma found aberrations in the region containing MYC in 75% of cases." (PMID 38133254, 2023). "Quantitative evaluation of MYC protein expression using the PID method stratified OS in patients with diffuse large B-cell lymphoma more precisely than the conventional IHC-DAB method." (PMID 37790929, 2023). "This is consistent with studies showing fimepinostat decreases MYC expression in diffuse large B-cell lymphoma and NUT midline carcinoma." (PMID 37098540, 2023). "Damaging mutations in primary cutaneous diffuse large B-cell lymphoma of the leg type, involving MYD88 gene, or BCL6 and MYC translocations or CDKN2A deletions are useful for diagnostic purposes." (PMID 36291756, 2022). "First, in diffuse large B-cell lymphoma, miR-34a expression is regulated in three ways: direct MYC mediation, epigenetic repression of the miR-34a promoter region, and miR-34a deletion." (PMID 36672841, 2022). "MYC-regulated NEAT1 was found to promote diffuse large B cell lymphoma (DLBCL) proliferation via the miR-34b-5p-GLI1 pathway." (PMID 34295338, 2021). "We developed a deep learning algorithm to detect MYC rearrangement in scanned histological slides of diffuse large B-cell lymphoma." (PMID 32979109, 2021).
diffuse large B-cell lymphoma (continued). "For example, the presence of MYC-IG rearrangement was identified as a predictor for treatment failure in patients with diffuse large B-cell lymphoma (DLBCL) who received immunochemotherapy." (PMID 34926267, 2021). "In a study published in 2019, a class of molecular high-grade diffuse large B-cell lymphoma (MHG) was defined, which had significantly higher mutation frequencies than GCB in KMT2D, BCL2, MYC, or DDX3X." (PMID 34925435, 2021). "In this review, we outline the current understanding of impaired immune responses in B cell lymphoid malignancies with MYC overexpression, with a particular emphasis on diffuse large B cell lymphoma." (PMID 33092116, 2020). "MYC gene rearrangements in diffuse large B cell lymphomas (DLBCLs) result in high proliferation rates and are associated with a poor prognosis." (PMID 31028445, 2019). "Rearrangements of MYC are seen in nearly 100% of BL but have been reported in 3–16% of diffuse large B-cell lymphomas (DLBCLs)." (PMID 28983465, 2017). "Our recent study showed that MYC rearrangements are detected in 9% of diffuse large B-cell lymphomas." (PMID 26416427, 2015). "Double-hit B cell lymphoma (DHL) is defined as diffuse large B cell lymphoma with translocations and/or extra signals involving MYC along with BCL2 and/or BCL6 as identified by FISH." (PMID 25918657, 2015). "MYC-driven double hit diffuse large B-cell lymphoma (DHL) is a molecularly defined subset with an aggressive clinical course that requires novel targeted combinations of agents to provide a high impact on survival." (PMID 24893165, 2014). "In typically MYC-driven Burkitt lymphoma, 7% (5/70) carry Notch1 mutations, 8% (5/63) of BCL2-associated diffuse large B-cell lymphoma (DLBCL) carry similar PEST mutations of Notch2, and 6% (2/35) had amplification of the Notch2 locus." (PMID 24959528, 2014). "It was tested in a phase 1 clinical trial for conditions such as cutaneous T-cell lymphoma (CTCL), chronic lymphocytic leukemia (CLL), and diffuse large B-cell lymphoma (DLBCL) which are known to be MYC-driven in a number of cases, and adult T-cell leukemia/lymphoma (ATLL)." (PMID 40126351, 2025). "MYC translocation occurs in 8–14% of diffuse large B-cell lymphoma (DLBCL), and may concur with BCL2 and/or BCL6 translocation, known as double-hit (DH) or triple-hit (TH)." (PMID 38184753, 2024). "In addition, MYC is involved in the histological transformation of indolent mature B-cell malignancies to aggressive diffuse large B-cell lymphoma (DLBCL)." (PMID 36966168, 2023). "Additionally, activation of the oncogenic transcription factor MYC is a common feature of diffuse large B‐cell lymphoma (DLBCL)." (PMID 37485814, 2023). "By contrast, unphosphorylated MYC binds to the microtubules of the mitotic spindle following vincristine treatment of diffuse large B cell lymphoma cells, allowing for transfer of functional MYC to dividing daughter cells, contributing to vincristine resistance and induction of polypoidy." (PMID 37345125, 2023). "In DLBCL (diffused large B-cell lymphoma) patients, 32% showed overexpression of MYC." (PMID 35401196, 2022). "High‐grade B‐cell lymphoma with MYC and BCL2 and/or BCL6 rearrangements (HGBL‐DH/TH) comprise ∼8% of tumors with diffuse large B‐cell lymphoma (DLBCL) morphology and is associated with poor outcome after standard R‐CHOP (rituximab, cyclophosphamide, doxorubicin, vincristine, and prednisone) therapy." (PMID 35846101, 2021). "We conducted a Phase 1 study of RO6870810 administered subcutaneously for 21 or 14 days of 28- or 21-day cycles, respectively, in patients with the nuclear protein of the testis carcinoma (NC), other solid tumours, or diffuse large B-cell lymphoma (DLBCL) with MYC deregulation." (PMID 33311588, 2021).
diffuse large B-cell lymphoma (continued). "A recent study has also already shown that the combination of a BET bromodomain inhibitor (which effectively downregulates MYC levels) with a specific BCL‐2 antagonist (ABT‐199) has synergistic antitumor activity in a xenograft mouse model of diffuse large B‐cell lymphoma (DLBCL)." (PMID 32623836, 2020). "In diffuse large B-cell lymphoma (DLBCL), concomitant overexpression of BCL-2 and MYC is classified as a “double-hit” DLBCL, which is associated with a dismal prognosis, high risk for relapse, resistance to standard chemotherapy and justifies upfront escalation to more intensive treatment." (PMID 32131385, 2020). "In line with a destabilized G1/S border as a common denominator for CHK1 inhibitor sensitivity, other groups have reported that MYC-driven diffuse large B cell lymphoma and CCND1-driven mantle cell lymphoma display a marked sensitivity against the CHK1 inhibitor PF-47773650,51." (PMID 29138515, 2017). "Activation of MYC is associated with increased proliferation, more aggressive disease and poorer outcomes in Richter's Transformation, a transformation of CLL into a clonally related aggressive Diffuse Large B Cell Lymphoma (DLBCL)." (PMID 27303665, 2016). "Whereas MYC translocation is found in almost all BL, it may be seen as well in some cases of diffuse large B-cell lymphoma (DLBCL) which is much more common, and may have a different treatment approach." (PMID 23762688, 2013). "In contrast, only 10% of diffuse large B-cell lymphomas (DLBCLs) harbor a MYC translocation." (PMID 22511926, 2012). "The tumor exhibited high proliferative activity and co-expression of BCL2 and MYC, consistent with a “double expressor” diffuse large B-cell lymphoma (DLBCL)." (PMID 40767831, 2025). "Gene expression profiling of germinal center B-cell diffuse large B-cell lymphoma can identify a double hit-like signature and inferior outcomes, but only half of these cases have structural rearrangements that can be detected by routine MYC and BCL2 break-apart FISH." (PMID 38903717, 2024). "While previous studies have shown the disruption of various cancer-associated mutations, our focus on targeting oncogenes such as PAX5, MYC, and CD79B in diffuse large B-cell lymphoma (DLBCL) represents a significant advancement." (PMID 39469218, 2024). "JQ1, I-BET, and OTX015 can significantly reduce the proliferation of MYC in diffuse large B-cell lymphoma (DLBCL) by targeting double-hit lymphoma (DHL)/triple-hit lymphoma (THL)." (PMID 36966168, 2023). "In other tumors, such as Burkitt’s lymphoma and subsets of diffuse large B-cell lymphoma (DLBCL) and multiple myeloma, MYC’s over-expression is a result of its translocation into immunoglobulin gene loci." (PMID 35203395, 2022). "Diffuse large B-cell lymphoma (DLBCL) with MYC/BCL2 double-expression (DE), a recently proposed poor prognostic group, can be easily identified by immunohistochemistry in routine clinical practice." (PMID 33182440, 2020). "Diffuse large B-cell lymphoma (DLBCL) patients with MYC/BCL2 double expression (DE) show poor prognosis and their clinical outcomes after R-CHOP therapy vary immensely." (PMID 33182440, 2020). "The effect of dual inhibition synergistically induced apoptosis of MYC-altered cells in diffuse large B-cell lymphoma (DLBCL)." (PMID 31093356, 2018). "The comparison between the gene expression profile (GEP) of BL and diffuse large B-cell lymphoma (DLBCL) highlighted a distinct signature of BL characterized by the expression of both MYC targets and germinal-center B-cell genes." (PMID 26468873, 2015). "Diffuse large B‐cell lymphoma typically expresses pan‐B markers CD19, CD20, CD22, CD79a, CD45RA, PAX5 markers, and other markers CD10, BCL6, BCL2, MYC, and MUM‐1." (PMID 40735721, 2025).
diffuse large B-cell lymphoma (continued). "We have demonstrated that AZ5576, a selective CDK9-inhibitor, led to rapid downmodulation of MYC and Mcl-1 in diffuse large B-cell lymphoma (DBLCL), accompanied by a shutdown of the MYC transcriptional program and apoptosis." (PMID 36998071, 2023). "Double-hit diffuse large B-cell lymphoma (DH-DLBCL) is an aggressive, and often refractory, type of B-cell non–Hodgkin lymphoma (NHL) characterized by rearrangements in MYC and BCL2." (PMID 37882668, 2023). "Diffuse large B-cell lymphoma (DLBCL) is a heterogeneous disease, with a variable response to chemotherapy depending on, and not limited to, cell of origin, double/triple hit, or MYC/BCL-2 co-expression status." (PMID 37641153, 2023). "In diffuse large B-cell lymphoma, CDK12 activated MYC to inhibit miR-28-5p/EZH2 and amplify BCR signaling to promote its progression." (PMID 36463205, 2022). "More specifically, roughly 80% of Burkitt’s lymphoma (BL), 15% of diffuse large B-cell lymphoma (DLBCL), and 2% of follicular lymphoma (FL) are characterized by MYC translocations." (PMID 36611833, 2022). "Diffuse large B‐cell lymphoma (DLBCL), the most common type of non‐Hodgkin lymphoma, is characterized by MYC rearrangements (MYC R) in up to 15% of cases, and these have unfavorable prognosis." (PMID 36051032, 2022). "Here we studied the relevance of the MYC/miR-150/MYB/ZDHHC11 network in two other GC B-cell derived lymphomas, i.e., Hodgkin lymphoma (HL) and diffuse large B-cell lymphoma (DLBCL)." (PMID 35205272, 2022). "An oncogenic role for DNMT3B is observed in several hematological cancers, including T-ALL, AML, and Burkitt and diffuse large B-cell lymphoma (DLBCL), where increased DNMT3B levels are reported to be mostly the result of increased MYC-levels." (PMID 36059621, 2022). "Besides, FIRRE is transcriptionally regulated by MYC and contributes to the proliferation and anti-apoptosis of diffuse large B-cell lymphoma (DLBCL) cells via the Wnt/β-catenin pathway." (PMID 34093813, 2021). "For example, it was found that MYC-regulated NEAT1 promoted diffuse large B-cell lymphoma (DLBCL) proliferation via the miR-34b-5p-GLI1 pathway, which could provide a novel therapeutic target for DLBCL." (PMID 35127729, 2021). "A diagnosis of diffuse large B-cell lymphoma in our therapeutic era should be implemented by the definition of the cell of origin, additional immunohistochemistry (i.e., BCL2 and MYC), and by fluorescent in-situ hybridization." (PMID 33050534, 2020). "Double expression of MYC and BCL2 proteins (DE) and double-hit MYC+BCL2/BCL6 translocations (DH) were established as important biomarkers in patients with diffuse large B-cell lymphoma (DLBCL) by the 2016 revision of the World Health Organization classification of lymphoid neoplasms." (PMID 29088292, 2017). "In this study, we assessed rearrangements and expression of MYC, BCL2 and BCL6 in 898 patients with de novo diffuse large B-cell lymphoma treated with standard chemotherapy (cyclophosphamide, doxorubicin, vincristine, and prednisone plus rituximab)." (PMID 26573234, 2016). "The adverse prognostic significance of double expressor (DE) status—defined by co‐expression of MYC and BCL2—and double‐hit/triple‐hit (DH/TH) status—characterized by translocations involving MYC and BCL2 and/or BCL6—is well established in nodal diffuse large B‐cell lymphomas." (PMID 41151993, 2026). "In addition, AID-induced hypermutations in oncogenes PIM1, MYC, RhoH/TTF (ARHH) and PAX5 are observed in more than 50% of diffuse large B-cell lymphomas." (PMID 40649888, 2025). "However, in a separate study on diffuse large B-cell lymphoma, GoF CARD11 mutants behaved as a “second-hit” to constitutively-expressed MYC in lymphomagenesis, suggesting CARD11 and MYC participate in independent but complementary pathways." (PMID 41346415, 2025).
diffuse large B-cell lymphoma (continued). "Similarly, although overexpression of the cell cycle regulator MYC and the anti-apoptosis protein BCL2 has prognostic value in the systemic diffuse large B-cell lymphoma, their significance in PCNLS remains uncertain." (PMID 39803131, 2024). "c-MYC and BCL2 positivity are important prognostic factors for diffuse large B-cell lymphoma." (PMID 38243330, 2024). "This is because most of what we know about DHLs is based on cases with MYC/BCL2 DHL, which has an inferior prognosis when treated with regimens for diffuse large B-cell lymphoma (DLBCL) and has a very high recurrence rate with a reported median survival of only 0.2 to 1.5 years." (PMID 30323893, 2018). "In humans, approximately 5% to 10% of diffuse large B-cell lymphomas harbor a MYC oncogene rearrangement and is considered to be a negative prognostic marker." (PMID 24023754, 2013). "A para-aortic LN biopsy revealed transformation to diffuse large B-cell lymphoma (DLBCL) with CD10 +, ki-67 proliferation index >90%, C-MYC >50%, FISH showing BCL2+, BCL6+, and MYC +." (PMID 41306534, 2025). "Fourteen years after initial diagnosis, she developed CNS symptoms with cerebellar lesions; resection revealed transformed diffuse large B-cell lymphoma (DLBCL) of germinal center origin (CD5+, CD10+, BCL2, BCL6, MYC+, Ki-67 ~70%)." (PMID 41146768, 2025). "Following a B-cell receptor activation and triggering of the PI3K/AKT signaling pathway, MYC-mediated PRMT5 transcription induces cell cycle progression, increasing cell survival and proliferation in both activated B-cell (ABC) and germinal center (GC) diffuse large B-cell lymphoma (DLBCL)." (PMID 36358861, 2022). "MYC/BCL2 protein co-expression (i.e., double expressor) has been shown to be a negative predictor of outcome in diffuse large B-cell lymphoma (DLBCL)." (PMID 34282799, 2021). "This study was designed to analyze the clinical characteristics and prognostic value of c-MYC and BCL-2 proteins expression in patients with primary central nervous system diffuse large B-cell lymphoma (PCNS-DLBCL)." (PMID 31702637, 2019). "Numerous studies have investigated the prognostic values of MYC and/or BCL2 protein overexpression in diffuse large B-cell lymphoma (DLBCL)." (PMID 29674626, 2018). "The isolated MYC+/BCL6+/BCL2− subset, more frequent in germinal center B-cell like diffuse large B-cell lymphoma, had significantly better survival compared with the isolated MYC+/BCL2+/BCL6− subset (more frequent in activated B-cell like diffuse large B-cell lymphoma)." (PMID 26573234, 2016). "Neither BCL6 translocation alone (more frequent in activated B-cell like diffuse large B-cell lymphoma) nor in combination with MYC translocation (observed in 2.0% of diffuse large B-cell lymphoma) predicted poorer survival in diffuse large B-cell lymphoma patients." (PMID 26573234, 2016). "The recent finding that MYC-driven cancers are sensitive to inhibition of the DNA damage response (DDR) pathway, prompted us to investigate the role of DDR pathway as therapeutic target in diffuse large B-cell lymphoma (DLBCL), which frequently overexpresses the MYC oncogene." (PMID 25544753, 2015). "Two independent pathologists confirmed the diagnosis of monomorhic PTLD, specifically diffuse large B-cell lymphoma (DLBCL), GCB subtype, “double expressor” phenotype, given the positive staining for BCL 2 positivity in ≥50% of tumor cells and MYC positivity in ≥40% of tumor cells." (PMID 41149073, 2025). "AZD4573 could downregulate multiple oncoproteins (MYC, Mcl-1, JunB, PIM3) and deregulate PI3K pathways in diffuse large B-cell lymphoma (DLBCL)." (PMID 38566153, 2024). "Herein we report a case of secondary CD20-negative diffuse large B-cell lymphoma (DLBCL) coexpressing MYC and BCL-2, which originated in middle ear." (PMID 30985716, 2019).